CTSE (cathepsin E)
Diseases named in the same sentence as CTSE in open-access papers (continued):
Sharing a sentence is not in itself a finding about the gene and the disease.
Parkinson disease (2 papers, 2017 to 2024). A progressive degenerative disorder of the central nervous system characterized by loss of dopamine producing neurons in the substantia nigra and the presence of Lewy bodies in the substantia nigra and locus coeruleus. "The study also found a causal relationship between Cathepsin D and Parkinson’s disease, as well as between Cathepsin E and both stroke and multiple sclerosis, and between Cathepsin O and stroke." (PMID 39420987, 2024).
amyloidosis (1 paper, 2017). A disorder characterized by the localized or diffuse accumulation of amyloid protein in various anatomic sites. "Based on these observations and since CtsE was found considerably reduced in injured V30M nerves, it is possible that this molecule might be involved in the mechanism contributing for the lower regenerative ability present in TTR V30M amyloidosis, which is under investigation." (PMID 28583160, 2017).
atherosclerosis (1 paper, 2024). A disease characterized by the build-up of fatty material and calcium deposition in the arterial wall resulting in partial or complete occlusion of the arterial lumen. "Thus, cathepsin E may increase the risk of MI and IS by promoting atherosclerosis." (PMID 39027333, 2024). "The impact of Cathepsin E on MI and IS is mainly achieved through the following three mechanisms: First, Inflammatory Modulation: Cathepsin E may exacerbate vascular inflammation, which is a critical component of atherosclerosis progression." (PMID 39027333, 2024).
Blindness (1 paper, 2022). Blindness is the condition of lacking visual perception defined as a profound reduction in visual perception. "The specificity of VHH‐B9 for BACE1 also avoids issues of impaired glucose homeostasis, hypopigmentation, seizures, and blindness (among others), which are associated with cross‐reactivity with BACE2, Cathepsin D, and Cathepsin E." (PMID 35352880, 2022).
colitis (1 paper, 2025). Inflammation of the colon. "In addition, 2′‐FL significantly rescued the abnormal downregulation of growth‐regulatory proteins cathepsin E (Ctse), lymphokine‐activated killer T‐cell‐originated protein kinase (Pbk), and chromosome‐associated kinesin KIF4 (Kif4) in DSS‐induced colitis mice." (PMID 40501496, 2025).
colorectal cancer (1 paper, 2021). A primary or metastatic malignant neoplasm that affects the colon or rectum. "In addition, it has also been suggested that the CTSE transcripts significantly increase (approximately 100-fold) in intestinal adenoma and carcinoma compared to normal epithelium, further highlighting the specific role of CTSE in colorectal cancer." (PMID 34357018, 2021).
COVID-19 (1 paper, 2021). A disease caused by infection with severe acute respiratory syndrome coronavirus 2. "Indeed, most recent proteomic analysis of COVID-19 autopsies suggested an overall upregulation of the cathepsin family members, including CTSB, CTSD, CTSE, CTSH, CTSK, CTSS, and CTSZ, in the lung of the COVID-19 patients." (PMID 34335974, 2021).
diabetes (1 paper, 2025). "For Cathepsin E, an intracellular, hydrolytic aspartic protease that is expressed in cells of the immune and gastrointestinal systems, lymphoid tissues, erythrocytes, and cancer cells, MVMR identified a diabetes subtype-independent risk association with PDR, absent in univariable analysis." (PMID 40616157, 2025).
dyslipidemia (1 paper, 2022). "However, the supplement with HFLPD inhibited DEGs of CTSE and DMBT1 in mice, suggesting that the probiotic supplement reduced the hepatic inflammation and dyslipidemia via the downregulation of these DEGs." (PMID 35743193, 2022). "The DEGs of CTSE and DMBT1 were significantly increased in response to HFD-fed animals, which confirmed that HFD might induce hepatic inflammation and dyslipidemia in mice liver by increasing the mRNA CTSE and DMBT1." (PMID 35743193, 2022).
dysplasia (1 paper, 2015). A usually neoplastic transformation of the cell, associated with altered architectural tissue patterns. "CTSE mRNA expression is up-regulated more than any known gene in Barrett intestinal metaplasia and dysplasia tissues." (PMID 25348778, 2015).
emphysema (1 paper, 2018). "Increased expression of DRP1 was found in a mouse emphysema model induced by over-expression of cathepsin E where inhibition of DRP1 prevented cell apoptosis and emphysema." (PMID 30466433, 2018).
gastric adenoma (1 paper, 2013). A neoplastic polyp that arises from the stomach. "It should be also noted that gastric adenoma, which can be considered as more differentiated histological feature compared with tub1-type GC, showed the strongest deficiency of CTSE." (PMID 23451082, 2013). "For gastric adenoma and tub1/tub2-type GC, more undifferentiated tumors tend to show higher expression of CTSE with MUC5AC and lower expression of MUC2 in tumors, but they tend to present lower expression of CTSE, MUC5AC and MUC2 in background mucosa." (PMID 23451082, 2013).
Hyperglycemia (1 paper, 2023). An increased concentration of glucose in the blood. "However, in both SC and SN in hyperglycemia, the expression of one, single gene, i.e. CTSE involved in neuronal death signaling pathway was affected." (PMID 37462767, 2023).
inflammatory bowel disease (1 paper, 2022). A spectrum of small and large bowel inflammatory diseases of unknown etiology. "CTSE was previously identified among the genes, which are uniquely expressed in ulcerative colitis phenotype of the inflammatory bowel disease." (PMID 36145641, 2022).
intrahepatic cholangiocarcinoma (1 paper, 2025). A carcinoma that arises from the intrahepatic bile duct epithelium in any site of the intrahepatic biliary tree. "Notably, a recent study on intrahepatic cholangiocarcinoma revealed co-localization of CTSE+ tumor cells with specific tumor-associated macrophages, jointly contributing to poor patient prognosis." (PMID 41301873, 2025).
liver cancer (1 paper, 2025). An epithelial or non-epithelial malignant neoplasm that arises from the liver. "We measured tumor size and weight, and the results demonstrated that CTSE knockdown inhibited tumor growth of liver cancer cells." (PMID 40467555, 2025). "Here, we report that CTSE is significantly upregulated in patients with advanced liver cancer and that patients with high CTSE expression have significantly shorter progression-free survival and overall survival, which is consistent with our findings." (PMID 40467555, 2025). "To investigate the role of CTSE in tumor growth and its regulatory impact on the immune microenvironment, we injected CTSE knockdown H22 cells into the livers of mice, establishing an in situ liver cancer model." (PMID 40467555, 2025).
lung carcinoma (1 paper, 2025). "The protein expression of CTSB and CTSE in lung cancer tissues from the KMS group was found to be lower than that in the KS group, as evidenced by western blotting and immunohistochemistry (IHC) analyses." (PMID 40057469, 2025). "Western blotting analysis showed that MEN1 shRNA-knockdown (KD) noticeably inhibited the expression of both the precursor (p) and mature (m) forms of CTSB and CTSE in the lung cancer cell lines (A549 and NCI-H157) and the immortalized bronchial epithelial cell line (16-HBE)." (PMID 40057469, 2025). "Here, SP2509 effectively restored the expression of genes such as CTSE and TFAM in the lung cancer of KMS mice, along with the restoration of H3K4me3." (PMID 40057469, 2025).
lung diseases (1 paper, 2023). "Correlations between cathepsin E and lung diseases have been reported." (PMID 37434162, 2023).
metastatic prostate carcinoma (1 paper, 2022). A carcinoma that arises from the prostate gland and has spread to other anatomic sites. "In addition, in silico analyses of publicly available genomic datasets of metastatic prostate cancer (including NEPCs) showed rare, mostly nonpathogenic, single-nucleotide variants and one case with a CTSE-ALK fusion." (PMID 36337169, 2022).
multiple sclerosis (1 paper, 2024). A progressive autoimmune disorder affecting the central nervous system resulting in demyelination. "Additionally, reverse MR indicated that multiple sclerosis is associated with reduced Cathepsin E levels." (PMID 39420987, 2024). "Reverse MR analysis indicates a correlation between multiple sclerosis and increased levels of Cathepsin E. Multiple sclerosis is a progressive inflammatory demyelinating disease of the central nervous system." (PMID 39420987, 2024). "Reverse MR analyses revealed that multiple sclerosis and Cathepsin E (OR: 1.05, 95%CI: 1.01, 1.10, p = 0.030)." (PMID 39420987, 2024).
nephritis (1 paper, 2020). Inflammation of renal tissue. "The following potential proteases for the different CKD aetiologies were identified: ADPKD (MMP7), MCD (CTSB, CTSD, CTSE, MEP1A, MMP7, PGA3), MGN (MMP3, MMP7, MMP9, MMP13, MMP14), IgAN (MMP7), FSGS (MMP3, MMP7), vasculitis (PGA3), nephritis (MMP7, MMP9), nephrosclerosis (MMP7), and DKD (MMP9)." (PMID 32427855, 2020).
pancreatic adenocarcinoma (1 paper, 2021). "Even as early as two decades ago, high levels of cathepsin E in pancreatic juice were suggested to be indicative of adenocarcinoma of the pancreas." (PMID 33802262, 2021). "High levels of cathepsin E are characteristic for lesions found in pancreatic adenocarcinoma and could be a valuable biomarker for early detection of pancreatic cancer, which is still very challenging to diagnose at an early stage." (PMID 33802262, 2021).
scrapie (1 paper, 2015). A fatal disease of the nervous system in sheep and goats, characterized by pruritus, debility, and locomotor incoordination. "For example, cathepsin E is up-regulated 5.6-fold in rat scrapie, but not differentially expressed (1.1-fold) in mouse scrapie." (PMID 26341492, 2015).
signet ring cell carcinoma (1 paper, 2013). A usually aggressive, poorly differentiated invasive adenocarcinoma characterized by the presence of malignant glandular cells in which the nucleus is pressed to one side by the presence of intracytoplasmic mucus. "In conclusion, CTSE is a marker of both gastric differentiation and signet-ring cell carcinoma, which should shed light on the mechanism of gastric tumorigenesis." (PMID 23451082, 2013).
thymoma (1 paper, 2021). A neoplasm arising from the epithelial cells of the thymus. "ZBTB33 binds to a motif in the Ctse locus in a methylation-dependent manner, and subsequently represses the expression of Cathepsin E and IL-10 in murine thymoma EL-4 cells, and in CD4+ T cells of MRL/lpr mice or patients with systemic lupus erythematosus (SLE)." (PMID 34349770, 2021).
tubular adenocarcinoma (1 paper, 2013). An infiltrating adenocarcinoma in which the malignant cells form tubular structures. "We then directed our attention to the CTSE, as it expresses in both Kato-III and NUGC-4 derived from sig-type GC, and also because it never expresses in MKN-7 and H-111-TC known to be originated from well differentiated tubular adenocarcinoma of stomach (tub1-type GC, Supporting Document S1)." (PMID 23451082, 2013).
tumor (33 papers, 2012 to 2025). "High CTSE expression (likely derived mainly from immune cells) signifies an active anti-tumor immune response and is associated with better prognosis." (PMID 41301873, 2025). "In contrast, CTSE expression was significantly associated with tumor size (p < 0.001), T stage (p < 0.001), and M stage (p = 0.001), but not with sex, age, N stage, or overall TNM stage." (PMID 41301873, 2025). "Univariate analysis further demonstrated significant associations among N stage, TNM stage, CTSE expression, and prognosis, while multivariate analysis confirmed tumor size and CTSE expression as independent prognostic factors." (PMID 41301873, 2025). "Then, we developed a novel diagnostic model using LAMC2, SLC6A14 and CTSE, which showed a strong predictive ability in screening PC specimens from non-tumor specimens in several GEO datasets." (PMID 38267509, 2024). "CTSE-deficient mice exhibit impaired immunity, with fewer tumor-infiltrating macrophages compared to controls." (PMID 39736788, 2024). "Similarly, univariate analysis for CTSE showed significant associations of tumor size (p = 0.001), N stage (p = 0.013), TNM stage (p = 0.029), and CTSE expression (p = 0.012) with OS." (PMID 41301873, 2025). "Spatial transcriptomics revealed the co-localization of MARCO+ TAMs with cathepsin E (CTSE+) tumor cells." (PMID 40507339, 2025). "To further investigate the role of CTSE expression in intra-tumoral immune cell infiltration, we constructed a subcutaneous tumor model in mice using the CTSE knockdown H22 cells." (PMID 40467555, 2025). "Although these results appear contradictory, we propose that they highlight the multifaceted role of CTSE within the complex tumor microenvironment of PC." (PMID 41301873, 2025). "Multicolor flow cytometry analysis revealed a significant intra-tumoral infiltration of CD8+ and IFNγ+CD8+ T cells in the tumor tissues of the CTSE knockdown group and anti-PD-1 combination treatment group." (PMID 40467555, 2025). "High infiltration of both MARCO+ TAMs and CTSE+ tumor cells correlated with the poorest survival outcomes." (PMID 40507339, 2025). "The results showed a significant reduction in T-cell infiltration in the tumor tissues of patients with high CTSE expression." (PMID 40467555, 2025). "Analysis of IHC staining showed that the expression levels of CD8, IFN-γ, and GZMB were significantly upregulated in tumor tissues with CTSE knockdown and the anti-PD-1 combination treatment group." (PMID 40467555, 2025). "Although CTSE is believed to influence tumor invasion and EMT, its role and specific mechanisms in PC have not yet been elucidated." (PMID 41301873, 2025). "In this study, we found that the tumor tissues of patients with high CTSE expression tended to exhibit a “cold” tumor microenvironment characterized by the absence of CD45+ immune cells." (PMID 40467555, 2025). "We analyzed a cohort of HCC patients with differential CTSE expression to map the transcriptomic landscape of tumor tissues, including the tumor core and tumor immune microenvironment, by a comprehensive digital spatial profiling (DSP) approach." (PMID 40467555, 2025). "Overall, low CTSE expression in tumor cells predicts better prognosis and inhibits tumor growth by recruiting the infiltration of T cells." (PMID 40467555, 2025). "The results indicated that CTSE knockdown inhibits tumor growth, the liver/ body weight ratio, and the tumor burden of mice." (PMID 40467555, 2025). "This dynamic equilibrium enables PC cells to survive and adapt under varying microenvironmental and physiological conditions by flexibly modulating the relative expression of CTSE and S100P, thereby influencing tumor progression and metastasis." (PMID 41301873, 2025). "To further analyze how the differential expression of CTSE in tumor cells impacts patient heterogeneity, we compared gene expression changes in PanCK+ cells from patients with high and low CTSE expression." (PMID 40467555, 2025).
tumor (continued). "To investigate the impact of differential CTSE expression on immune cell infiltration and its regulatory role, we compared the immune cell infiltration in tumor tissues between patients with high and low CTSE expression." (PMID 40467555, 2025). "We found that the expression of LAMC2, SLC6A14 and CTSE was distinctly increased in PC specimens and exhibited a dysregulated level in many types of tumors, suggesting their important function in tumor progression." (PMID 38267509, 2024). "In 106 pairs of BCa tissues, we observed an upregulation of both CTSE mRNA and protein levels in tumor tissues, which was further supported by representative IHC images." (PMID 37325625, 2023). "qRT-PCR, immunoblotting, and immunohistochemistry assays showed the enhanced expression of CTSE in BCa tumor tissues." (PMID 37325625, 2023). "In our study, we observed higher expression levels of CTSE at both mRNA and protein levels in BCa tumor tissues." (PMID 37325625, 2023). "Very consistently, there are elevated anti-tumor molecules such as perforin, granzyme B, CTSE and increased Th1 transcription factor T-bet while decrease of Th1 inhibitory molecule like SOCS1 and Twist1 in the lung of CD4-Chi3l1 KO mice." (PMID 29403003, 2018). "Mice overexpressing cathepsin E demonstrated enhanced tumor growth and metastasis through induction of the EMT process." (PMID 26718772, 2016). "The CTSE, an aspartic protease, plays a role in suppressing cell growth and metastasis in tumor cells." (PMID 25932638, 2015). "For sig-type GC, both the tumor lesion and background mucosa mostly showed strong expression of CTSE and MUC5AC, whereas expression of MUC2 was very weak in both of them." (PMID 23451082, 2013). "Strikingly, obvious staining of CTSE was observed in all the 51 specimens examined, and in 50 of 51 cases, CTSE-positive cells occupied more than 90% of cancer cells in the tumor." (PMID 23451082, 2013). "Cathepsin E, which usually operates at acidic pH, has been shown to induce cancer cell apoptosis and inhibit tumor angiogenesis at neutral pH, which promotes the finding of its activators for cancer therapy." (PMID 23365585, 2012). "However, the functional role of CTSE appears to vary under different conditions, highlighting that CTSE can impede tumor growth and metastasis through modulation of IL-12 and endostatin, thereby influencing angiogenesis." (PMID 40467555, 2025). "CTSE expression was also correlated with tumor size, as well as T and M stages." (PMID 41301873, 2025). "Only one primary tumor and three lymph node metastases showed Cathepsin E expression." (PMID 36835265, 2023). "Subsequently, owing to the overexpression of endogenous CTSE in tumor sites, fluorescence signals were distinctly observed in the tumor site upon intravenous or intra-tumoral administration of QM-HSP-CPP for 4 h and remained at almost the same intensities within 8 h." (PMID 35745035, 2022). "At the univariate level, CTSE overexpression in tumor specimens was an unfavorable prognostic factor for all three endpoints: disease-specific survival (DSS), metastasis-free survival (MeFS) (both p < 0.0001), and local recurrence-free survival (LRFS) (p = 0.0001)." (PMID 34357018, 2021). "In addition, tumors with CTSE overexpression had a remarkably lesser degree of tumor regression (p = 0.003)." (PMID 34357018, 2021). "Consistent with the RNA-sequencing and RT-PCR results, Chi3l1 KO mice had increased mRNA for anti-tumor immunity molecules including CTSE, TRAL, IFNγ, T-bet, Perforin, and Granzyme B, while the expression of Th1-inhibitory molecules such as Twist1 and SOCS1 was significantly reduced." (PMID 29403003, 2018). "In a backward stepwise regression model including sex, age, overall tumor stage, and CTSE expression below the 25th percentile, only age (HR 1.04, 95 % CI 1.00–1.08; p = 0.04) and AJCC stage II (HR 4.93, 95 % CI 1.88–12.88; p = 0.001) were independent prognostic markers for decreased survival." (PMID 25348778, 2015).